RIPK4 (receptor interacting serine/threonine kinase 4)
Diseases named in the same sentence as RIPK4 in open-access papers (continued):
Sharing a sentence is not in itself a finding about the gene and the disease.
hepatocellular carcinoma (7 papers, 2015 to 2023). A malignant tumor that arises from hepatocytes. "Intriguingly, recent genetic evidence in mouse skin tumor models and cell lines supports a tumor suppressor function of RIPK4 in skin, lung and hepatocellular carcinoma." (PMID 37688617, 2023). "RIPK4 expression is confirmed to be positively associated with favorable prognosis in tongue SCC, lung adenocarcinoma, and hepatocellular carcinoma." (PMID 35186499, 2022). "In contrast, decreased expression of RIPK4 was found in hepatocellular carcinoma and tongue squamous cell cancer." (PMID 33855091, 2021). "The RIPK4-overexpressing hepatoma cell lines also showed more epithelial cell-like morphology than other cell groups." (PMID 34222329, 2021). "RIPK4 was significantly suppressed in 80% of the hepatocellular carcinoma (HCC) samples, and RIPK4 overexpression resulted in almost complete elimination of anchorage-independent growth in the already transformed human fetal hepatocytes." (PMID 32923402, 2020). "However, the expression of RIPK4 is down-regulated and positively correlates with favorable prognosis in tongue SCC, hepatocellular carcinoma (HCC) and lung adenocarcinoma." (PMID 35186499, 2022).
lung adenocarcinoma (6 papers, 2017 to 2023). A carcinoma that arises from the lung and is characterized by the presence of malignant glandular epithelial cells. "In a mouse model of lung adenocarcinoma, RIPK4 suppression resulted in cancer dedifferentiation and in human lung adenocarcinoma patient low RIPK4 mRNA levels were associated with poor tumor differentiation and reduced overall survival." (PMID 37688617, 2023). "Besides, RIPK4 is associated with STAT3 signaling that is activated in tumor metastasis by regulating extracellular matrix remodeling enzymes in lung adenocarcinoma." (PMID 34124253, 2021). "Furthermore, bioinformatics analyses of human lung adenocarcinoma samples indicated that poorly differentiated tumors express significantly lower levels of RIPK4, which was associated with poorer overall survival." (PMID 32923402, 2020). "RIPK4 expression is positively associated with favorable prognosis in tongue SCC and lung adenocarcinoma." (PMID 32923402, 2020).
nasopharyngeal carcinoma (6 papers, 2020 to 2022). A carcinoma arising from the nasopharyngeal epithelium. "In nasopharyngeal carcinoma, RIPK4 is found to enhance the interaction between IKKβ and IKKα and activate NF-kB signaling pathway." (PMID 35186499, 2022). "Moreover, in nasopharyngeal carcinoma, RIPK4 can activate the NF-κB signaling pathway by interacting with the IKK complex to accelerate tumorigenesis and metastasis." (PMID 34124253, 2021). "RIPK4 overexpression promoted the growth of nasopharyngeal carcinoma (NPC) cells." (PMID 32923402, 2020). "And there are some studies that showed that RIPK4 can facilitate the differentiation of epidermis through phosphorylation and participate in the carcinogenesis of skin and encouraged the occurrence of nasopharyngeal carcinoma (Gong, Luo, Yang, Jiang, & Liu, 2018)." (PMID 31273792, 2020). "Studies have shown that RIPK4 is upregulated in nasopharyngeal carcinoma tissues and facilitates the progression of tumours by promoting the expression of VEGF in nasopharyngeal carcinoma cells." (PMID 34222329, 2021).
tongue squamous cell carcinoma (6 papers, 2017 to 2023). A squamous cell carcinoma that arises from the tongue. "It was also noteworthy that RIPK4 expression was reduced in tongue SCC and its expression was positively associated with a favorable prognosis." (PMID 32923402, 2020). "In tongue squamous cell carcinoma, RIPK4 is confirmed to act as a promising biomarker for prognosis and treatment." (PMID 34124253, 2021). "However, the silencing of RIPK4 in tongue squamous cell carcinoma cells sensitized them to the actions of cisplatin." (PMID 36765875, 2023). "However, RIPK4 is found in well-differentiated tongue squamous cell carcinoma samples, and the level is significantly higher than that in poorly differentiated tongue squamous cell carcinoma samples." (PMID 34222329, 2021). "It was in accordance with our study that no matter the RIPK4 expression level was upregulated or downregulated, there were no significant changes of apoptosis or cell cycle progression in human tongue SCC cell line Tca-8113." (PMID 35186499, 2022).
Bartsocas-Papas syndrome (5 papers, 2017 to 2025). "This mutation, located outside the kinase domain, differs from typical mutation sites in Bartsocas-Papas syndrome, suggesting that different locations of RIPK4 mutations may lead to varying degrees of phenotype severity." (PMID 39833848, 2025). "Loss of function mutations in RIPK4 have been identified in patients with a popliteal-pterygium syndrome (Bartsocas-Papas syndrome) characterised by numerous craniofacial, musculoskeletal, genitourinary, gastrointestinal, cardiac and neurodevelopmental defects, resembling IKKα deficiency." (PMID 36733767, 2022). "In addition, the RIPK4 p.Ile121Asn missense mutation, which has been identified in Bartsocas-Papas syndrome, inhibits the kinase activity of RIPK4, thereby abolishing RIPK4-mediated IRF6 and NF-κB activation." (PMID 32923402, 2020). "RIPK4 mutations have been linked to Bartsocas-Papas syndrome (BPS) in human, which is typically characterized by aberrant skin, craniofacial and genital development, and early death." (PMID 32923402, 2020). "While the kinase function of IKKα is dispensable for keratinocyte differentiation, RIPK4 phosphorylates IRF6 to drive nuclear translocation and regulate its transactivator activity; mutations in the kinase domain of RIPK4 that underlie Bartsocas Papas syndrome disrupt this activity." (PMID 35226783, 2022).
breast carcinoma (5 papers, 2015 to 2024). "Increased RIPK4 expression was found to be associated with lower overall survival in breast cancer and ovarian serous carcinoma." (PMID 26148476, 2015). "Meta-analysis confirmed RIPK4 as a significantly correlated gene with poor survival in breast cancer." (PMID 38744952, 2024). "Our findings highlight the significance of arm-level SCNAs in breast cancer progression and identify RIPK4 as a putative driver of TNBC metastasis and immunosuppression." (PMID 38744952, 2024). "RIPK4 overexpression significantly reduced migration and invasion capacity of human breast cancer cell line MCF7 (Zhang, He & Zhang, 2019)." (PMID 35186499, 2022). "Consistent with our findings, RIPK4 might be involved in the process of bone metastasis from breast cancer." (PMID 35186499, 2022). "For RIPK4, their relationship to breast cancer still remains unreported." (PMID 30918839, 2019). "To assess how RIPK4 expression may affect tumor cells, we leveraged the publicly available RNA sequencing data from the Cancer Cell Line Encyclopedia and divided 47 breast cancer cell lines based on RIPK4 expression." (PMID 38744952, 2024). "However, their function in breast cancer has been investigated except RIPK4." (PMID 30918839, 2019). "However, RIPK4 may only play an oncogenic role in Wnt-dependent tumors, since RIPK4 knockdown do not affect Wnt3a-induced β-catenin accumulation in pancreatic, kidney, and breast cancer cells." (PMID 35186499, 2022). "Among which, IBSP, MMP9, TNFAIP6, DHRS3, RIPK4, and CD200 had a diagnose value for patients with breast cancer bone metastasis." (PMID 30918839, 2019). "Conversely, RIPK4 displays heightened expression levels in most cancers, except for GBM, breast cancer (BRCA), liver hepatocellular carcinoma (LIHC), skin cutaneous melanoma (SKCM), ACC, and KICH, where it exhibits decreased expression levels relative to normal tissues." (PMID 38164277, 2024). "The research of TNFAIP6, DHRS3, ASS1, RIPK4, VIM, and CD200 in breast cancer may indicate that those genes may play a crucial role in the development of breast cancer bone metastasis." (PMID 30918839, 2019). "All the mRNA level of tested genes from adjacent non-tumor breast cancer was significantly different from metastasis tumor tissues, except RIPK4." (PMID 30918839, 2019). "Understanding the role of RIPK4 and its impact on the tumor immune microenvironment may provide insights into TNBC progression and offer potential therapeutic targets for this aggressive form of breast cancer." (PMID 38744952, 2024). "Besides some published potential biomarkers of breast cancer bone metastasis were identified in our study, we also detected some novel biomarkers or their relationship with breast cancer bone metastasis has never been reported, such as TNFAIP6, DHRS3, ASS1, RIPK4, VIM, CD200." (PMID 30918839, 2019).
cutaneous squamous cell carcinoma (4 papers, 2022 to 2024). "The cutaneous squamous cell carcinomas data deposited in TCGA and the assays of metastatic squamous cell carcinomas reported a similar high rate of RIPK4 mutagenesis." (PMID 35310605, 2022). "By large-scale genomic sequencing analysis, RIPK4 mutations have been identified in cutaneous squamous cell carcinoma (SCC), esophageal SCC, human papillomavirus (HPV)-positive oral SCC, and head and neck SCC, implicating a critical function of RIPK4 in squamous differentiation and carcinogenesis." (PMID 35186499, 2022). "There have been no studies exploring the effects of RIPK4 on the signaling pathway in cutaneous squamous cell carcinoma (SCC)." (PMID 35186499, 2022).
osteosarcoma (4 papers, 2020 to 2022). A usually aggressive malignant bone-forming mesenchymal neoplasm, predominantly affecting adolescents and young adults. "RIPK4 is also significantly upregulated in osteosarcoma and RIPK4 knockdown suppress epithelial to mesenchymal transition (EMT) by inactivating Wnt signaling." (PMID 35186499, 2022). "In osteosarcomas, silencing of RIPK4 inhibited EMT by inactivating the Wnt/β-catenin signaling pathway." (PMID 34768934, 2021). "In addition, RIPK4 was significantly upregulated in osteosarcoma and RIPK4 knockdown suppressed EMT by inactivating Wnt/β-catenin signaling." (PMID 32923402, 2020).
skin cancer (4 papers, 2015 to 2023). "In mouse transgenic skin cancer models expressing an activating mutant of phosphatidylinositol 3-kinase alpha (PIK3CAH1047R) or HRas (HRasG12V), mutations known to drive human SCC, a RIPK4 kinase-dependent tumor suppressor role was shown." (PMID 37688617, 2023). "Significantly upregulation of RIPK4 was also identified in ovary and skin tumors." (PMID 33487072, 2021). "However, our results are consistent with skin cancer studies in which RIPK4 acts as a tumor suppressor but does not affect signaling through this pathway." (PMID 36765875, 2023).
squamous cell carcinoma (4 papers, 2020 to 2024). A carcinoma arising from squamous epithelial cells. "For instance, RIPK4 mutations were observed in several squamous cell carcinomas." (PMID 35310605, 2022). "We directed our attention to the kinase RIPK4, which has been shown to enhance sensitivity towards CisPt treatment of Tca-8113 cells in squamous cell carcinoma of the tongue." (PMID 39766280, 2024). "The aim of our study is to understand the signaling mechanisms behind the tumor suppressive function of RIPK4 (receptor-interacting serine/threonine protein kinase 4) in squamous cell carcinomas (SCCs) of skin, head, and neck regions." (PMID 36765696, 2023). "In several types of squamous cell carcinoma (SCC), the mutations that drive aggressive SCC have been found in RIPK4." (PMID 32923402, 2020).
cutaneous melanoma (3 papers, 2021 to 2024). A primary melanoma arising from atypical melanocytes in the skin. "To explore the relationship between NFκB and RIPK4 expression, we performed immunohistochemical analysis of RIPK4 levels along with immunofluorescence for the p65 subunit of NFκB in clinical specimens of cutaneous melanomas." (PMID 38656555, 2024).
diffuse large B-cell lymphoma (3 papers, 2020 to 2023). "RIPK4 regulates constitutive NF-κB activity as well as NF-κB activation induced by B cell–activating factor of tumor necrosis factor family (BAFF) in diffuse large B-cell lymphoma (DLBCL) cells." (PMID 35186499, 2022). "RIPK4 was required for the survival of human diffuse large B-cell lymphoma (DLBCL) cells primarily through controlling NF-κB activation induced by the B cell-activating factor of the tumor necrosis factor family (BAFF)." (PMID 32923402, 2020). "In addition, RIPK4 knockdown in diffuse large B-cell lymphoma (DLBCL) cells was shown to impair cell survival, inhibit tumor growth in xenograft experiments as well as sensitize the cells to chemotherapeutic treatment, probably due to inhibition of RIPK4-induced NF-κB activity." (PMID 37688617, 2023).
lung carcinoma (3 papers, 2017 to 2021). "The loss of RIPK4 enhanced the STAT3 pathway in lung cancer cells and promoted the expression of extracellular matrix (ECM) remodeling genes." (PMID 32923402, 2020). "Quite strikingly, RIPK4 knockdown leading to lung cancer dedifferentiation was NF-κB independent and the potential of RIPK4 in reducing lung cancer cells metastases was kinase-independent." (PMID 32923402, 2020).
tongue cancer (3 papers, 2015 to 2020). A malignant neoplasm affecting the tongue. "RIPK4 knockdown enhanced migration and invasion capabilities of tongue cancer cells, thus implying that RIPK4 might be a tumor suppressor." (PMID 32923402, 2020). "Additionally, RIPK4 expression has been shown to reduce the migration and invasion in Tca-8113 tongue cancer cells." (PMID 26148476, 2015).
colon cancer (2 papers, 2016 to 2023). "To confirm that the observation that FIH regulates RIPK4-driven TCF/LEF transcriptional activity in other systems, we repeated the luciferase reporter assay in RKO cells, a colon cancer cell line which has not been shown to have a mutated Wnt-signaling pathway." (PMID 26972000, 2016).
Down syndrome (2 papers, 2010 to 2023). "DSCAM and RIPK4 have known relations to Down’s syndrome; since the association of Down's syndrome and leukemia has been documented for over 70 years, it is not surprising that DSCAM and RIPK4 are also grouped in this cluster." (PMID 21044360, 2010).
esophageal SCC (2 papers, 2020 to 2022). "In addition, RIPK4 point mutation was observed in esophageal SCC and RIPK4 was thus considered as the driver gene for this malignancy." (PMID 32923402, 2020).
lymph node metastasis (2 papers, 2021). "In serous ovarian cancer, the expression of RIPK4 in high-grade cancer tissues was obviously higher than that in low-grade cancer tissues, and lymph node metastasis and late clinical stage were also significantly correlated with high RIPK4 immunological reactivity (P = 0.003, respectively)." (PMID 33855091, 2021).
metastatic disease (2 papers, 2021 to 2024). "Since mortality of BC patients is linked to metastatic disease and the lungs represent a common metastatic site, we focused our attention on the role of RIPK4 on TNBC dissemination." (PMID 38744952, 2024).
metastatic melanoma (2 papers, 2021 to 2023). A melanoma that has spread from its primary site to another anatomic site. "To investigate whether BRAF protein mutations affect the RIPK4 expression level in metastatic melanoma, we analyzed clinical samples." (PMID 36765875, 2023). "We did not observe statistically significant differences in the RIPK4 protein expression in metastatic melanoma between those with or without BRAF mutations." (PMID 36765875, 2023). "Our attention was drawn to the kinase RIPK4; it has structural similarity to the BRAF protein and is highly expressed in some primary and metastatic melanoma specimens and cell lines." (PMID 36765875, 2023).
popliteal pterygium syndrome (2 papers, 2023). A rare, autosomal dominant inherited syndrome caused by mutations in the IRF6 gene. "Homozygous mutations in RIPK4 cause the autosomal recessive form of Popliteal Pterygium Syndrome (PPS), the Bartsocas Papas syndrome (BPS)." (PMID 37688617, 2023). "These differentially expressed genes include Ripk4, a gene whose disruption has been implicated in human popliteal pterygium syndromes." (PMID 37143038, 2023). "Disruption of Ripk4 in humans can result in popliteal pterygium syndrome, a condition in which abnormal skin fusions can occur under the arms and between the legs." (PMID 37143038, 2023).
psoriasis (2 papers, 2019 to 2024). An autoimmune condition characterized by red, well-delineated plaques with silvery scales that are usually on the extensor surfaces and scalp. "RIPK4 expression levels are higher in keratinocytes in psoriasis lesions than in healthy control skin, and stimulation with IL-17 induces RIPK4 expression in keratinocytes." (PMID 31156649, 2019).
squamous cell carcinoma of the skin (2 papers, 2021). "For example, a study about squamous cell carcinoma of the skin shows that RIPK4 is helpful for the discovery of cancer pathogenesis and for potential treatments." (PMID 34124253, 2021).
arthrogryposis multiplex congenita (1 paper, 2025). Arthrogryposis multiplex congenita (AMC) is a group of disorders characterized by congenital limb contractures. "Our study reported a case of Arthrogryposis Multiplex Congenita (AMC) and identified two novel RIPK4 variants (c.1354G > A:p.E452K and c.1558A > T:p.T520S) through Whole Exome Sequencing (WES) and Sanger sequencing." (PMID 39833848, 2025). "Notably, two novel variants (c.1354G > A, p.E452K; c.1558A > T, p.T520S) in the RIPK4 gene, associated with Arthrogryposis Multiplex Congenita (AMC), were unearthed." (PMID 39833848, 2025).
B cell lymphoma (1 paper, 2015). "Interestingly, Ripk4, a receptor-interacting serin-threonine kinase known to play a role in inflammatory cutaneous processes as well as B cell lymphoma, is highly downregulated." (PMID 25880204, 2015).
Cerebellar hypoplasia (1 paper, 2023). Cerebellar hypoplasia is a descriptive term implying a cerebellum with a reduced volume, but a normal shape and is stable over time. "Comparing these four models suggests that at least one gene in the region that is trisomic in both Ts1Cje and Ts65Dn mice but is not trisomic in Ts1Rhr mice (Sod1 to Setd4 and Ripk4 to Zbtb21) contributes to cerebellar hypoplasia." (PMID 36995257, 2023).
cervical SIL (1 paper, 2015). "For this reason, RIPK4, especially the combination of RIPK4 and p16INK4a, with increased specificity for HSIL could help to more accurately diagnose, focus medical resources and avoid overtreatment of patients with cervical SIL." (PMID 26148476, 2015).